FAM111B (FAM111 trypsin like peptidase B)
Description:
Serine protease.
Synonyms: CANP; POIKTMP
Tractability: PROTAC: UniProt records ubiquitination sites on it; ubiquitination databases record sites on it.
Gene: Protein-coding gene on chromosome 11 (59,107,185 to 59,127,415, forward strand). Ensembl gene ENSG00000189057.
Subcellular location (Human Protein Atlas): Nucleoplasm; Cytosol
Gene Ontology:
Molecular function: protein binding; serine-type peptidase activity
Biological process: protein-DNA covalent cross-linking repair; replication fork processing
Cellular component: cytoplasm; nuclear lamina; nucleus; chromatin
Genetic constraint (gnomAD): Loss-of-function variants: 2 observed, 2.51 expected, observed/expected ratio (o/e) 0.8, 90% interval 0.31 to 1.82. That is too few expected variants to judge how well the gene tolerates losing a copy. Missense variants: 848 observed, 891.72 expected, observed/expected ratio (o/e) 0.95, 90% interval 0.9 to 1.01. Synonymous variants: 284 observed, 303.67 expected, observed/expected ratio (o/e) 0.94, 90% interval 0.85 to 1.03.
Gene-disease validity (ClinGen):
ClinGen rates the evidence that FAM111B causes each of these diseases.
hereditary sclerosing poikiloderma with tendon and pulmonary involvement (autosomal dominant): Moderate.
Homologues: Orthologues: chimpanzee FAM111B (99% identical), macaque FAM111B (91% identical), dog FAM111B (62% identical), pig FAM111B (57% identical), zebrafish fam111.2 (11% identical). Paralogues in human: FAM111A (30% identical).
Diseases named in the same sentence as FAM111B in open-access papers:
FAM111B is named in the same sentence as 47 diseases in open-access papers, as found by Europe PMC text mining. Sharing a sentence is not in itself a finding about the gene and the disease. The quoted sentences say what the papers report.
pulmonary fibrosis (11 papers, 2015 to 2025). Chronic progressive interstitial lung disorder characterized by the replacement of the lung tissue by connective tissue, leading to progressive dyspnea, respiratory failure, or right heart failure. "Poikiloderma, hereditary fibrosing, with tendon contractures, myopathy, and pulmonary fibrosis (POIKTMP) is a rare genetic multisystemic fibrosing disorder caused by FAM111B gene mutations." (PMID 40840166, 2025). "FAM111B gene mutations are associated with a hereditary fibrosing poikiloderma known to cause poikiloderma, tendon contracture, myopathy, and pulmonary fibrosis (POIKTMP)." (PMID 35860584, 2022). "Mutations in FAM111B have been associated with the development of hereditary fibrosing poililoderma with pulmonary fibrosis, tendon contracture and myopathy." (PMID 27070714, 2016). "We report a series of ten families of HFP with muscle contractures, myopathy, and pulmonary fibrosis due to dominant mutations in the FAM111B gene." (PMID 26471370, 2015). "HFP with tendon contractures, myopathy and pulmonary fibrosis, is a multisystemic disorder due to autosomal dominant FAM111B mutations." (PMID 26471370, 2015). "Moreover, mutations in FAM111B cause hereditary fibrous dermatosis combined with tendon contracture, myopathy, and pulmonary fibrosis, as well as hereditary pancreatic exocrine dysfunction, among other disorders." (PMID 36004205, 2022). "We have discovered that mutations in family with sequence similarity 111, member B (FAM111B) gene cause hereditary fibrosing poikiloderma with tendon contractures, myopathy, and pulmonary fibrosis, a multisystem fibrotic condition with clinical similarities to SSc." (PMID 30375432, 2018). "Mutations in the FAM111B gene may predict the severity of pulmonary fibrosis and a poor prognosis." (PMID 40357364, 2025). "Autosomal dominant mutations found in the FAM111B gene are the primary cause of hereditary fibrosing poikiloderma with tendon contractures, myopathy, and pulmonary fibrosis (POIKTMP), a rare disorder with 37 confirmed cases." (PMID 36589246, 2022). "Hereditary fibrosing poikiloderma with tendon contractures, myopathy, and pulmonary fibrosis (POIKTMP) is a recently described genetic disorder, caused by mutation in FAM111B, which is inherited in an autosomal dominant manner." (PMID 35601499, 2022). "We previously identified HFP with tendon contractures, myopathy, and pulmonary fibrosis (POIKTMP) as a new clinical entity and we identified the causative mutations in the FAM111B gene (NM_198947.3) by whole-exome sequencing." (PMID 26471370, 2015).
lung adenocarcinoma (7 papers, 2022 to 2025). A carcinoma that arises from the lung and is characterized by the presence of malignant glandular epithelial cells. "The overexpression of the FAM111B gene is linked to various cancers, including lung adenocarcinoma, fibrosarcoma, and breast and ovarian cancers." (PMID 38474092, 2024). "Moreover, mutations and elevated expression levels of FAM111B have been linked to various fibrotic conditions and malignancies, such as pulmonary fibrosis, thyroid cancer, and lung adenocarcinoma." (PMID 40390043, 2025). "Previous studies have indicated that FAM111B overexpression is correlated with advanced and unfavorable prognoses in various cancers, including pancreatic cancer and lung adenocarcinoma." (PMID 40390043, 2025). "This action facilitates cell cycle progression and cellular proliferation, positioning FAM111B as a potential prognostic marker for lung adenocarcinoma." (PMID 40390043, 2025). "FAM111B has been identified as an oncogene in several types of cancer, including pancreatic adenocarcinoma, lung adenocarcinoma, bladder cancer, and hepatocellular carcinoma." (PMID 40781291, 2025). "For instance, the expression of FAM111B demonstrates a positive correlation with the infiltration of multiple immune cell subtypes and the expression levels of immune checkpoint markers in lung adenocarcinoma." (PMID 40564014, 2025). "The upregulation of the FAM111B protein is identified in specific subtypes of lung adenocarcinoma such as papillary-predominant adenocarcinoma and is correlated with unfavorable overall survival outcomes." (PMID 40781291, 2025). "In addition, the overexpression of FAM111B in lung adenocarcinoma (LUAD) patients correlated strongly with increased tumor progression and poor survival rate." (PMID 35860584, 2022). "Recent research suggests that FAM111B is crucial as a modulator of the TIME in various cancers, such as lung adenocarcinoma, renal clear cell carcinoma, head and neck squamous cell carcinoma, thymoma, and uveal melanoma." (PMID 40564014, 2025). "For example, in lung adenocarcinoma, FAM111B modulates the expression of BCL2 and BAG3 to facilitate cell proliferation, and FAM111B exhibits peak expression levels during the early G0 phase and late S phase of the cell cycle." (PMID 40781291, 2025).
ovarian carcinoma (6 papers, 2024 to 2025). A malignant neoplasm originating from the surface ovarian epithelium. "While the FAM111B gene has been implicated in various cancer types, its specific role in ovarian cancer remains poorly understood." (PMID 40781291, 2025). "To verify the role of FAM111B in DNA repair pathways, we transfected ES-2 ovarian cancer cells with FAM111B siRNA lentivirus to silence FAM111B expression." (PMID 40243892, 2025). "Taken together, these findings indicate that the inhibition of FAM111B hinders the viability and proliferation of ovarian cancer cells." (PMID 40781291, 2025). "Further investigation into pathways demonstrated that FAM111B was linked to the tumor proliferation signature (R = 0.51, P < 0.001), MYC pathway (R = 0.32, P < 0.001), and the EMT (R = 0.20, P < 0.001) in ovarian cancer." (PMID 40781291, 2025). "To assess the impact of FAM111B on the migratory and invasive properties of ovarian cancer cells, we conducted Transwell assays; and our results indicated a notable decrease in the migratory capacity of FAM111B-silenced cells compared to the shCtrl group." (PMID 40781291, 2025). "In human cancers, overexpression of FAM111B has been reported in multiple cancer types, e.g., esophageal cancer, hepatocellular carcinoma, bladder cancer, ovarian cancer, breast cancer and lung cancer." (PMID 39337462, 2024). "Nevertheless, the precise role of FAM111B remains unclear, and its potential involvement in the pathogenesis of ovarian cancer has yet to be established conclusively." (PMID 40781291, 2025). "Additionally, protein transcriptomic analysis implicated FAM111B in genetic-information processing via the MYC pathway, underscoring FAM111B’s central role in ovarian cancer tumorigenesis." (PMID 40781291, 2025). "Consequently, elevated expression of FAM111B, acting as an oncogene, is acknowledged to facilitate malignant biological mechanisms in ovarian cancer." (PMID 40781291, 2025). "We propose that targeting FAM111B gene holds potential therapeutic implications for ovarian cancer." (PMID 40781291, 2025). "In this study, we examined the role of FAM111B in ovarian cancer through in vitro and in vivo experiments, and our analysis of FAM111B protein levels in tissue microarray samples revealed a correlation between elevated FAM111B expression and unfavorable patient outcomes." (PMID 40781291, 2025). "Consequently, further validation of these compounds and molecules is warranted to explore novel targeted therapeutic approaches for ovarian cancer characterized by high FAM111B expression." (PMID 40781291, 2025). "We herein observed that FAM111B knockdown attenuated tumor growth both in vitro and in vivo in ovarian cancer, with results aligning with a previous study that illustrated the impact of FAM111B suppression on tumor growth, G1/S phase cell-cycle arrest, and apoptosis in ovarian cancer." (PMID 40781291, 2025). "Our in vitro experiments indicated that the inhibition of FAM111B resulted in reduced cellular proliferation, migration, invasion, and EMT in ovarian cancer cell lines and in the suppression of tumor growth in a mouse xenograft model." (PMID 40781291, 2025). "In our previous study, we demonstrated that FAM111B is significantly overexpressed in ovarian cancer (OV) compared to adjacent non-cancerous tissues, and that its expression is linked to an aggressive pathology and poor prognosis." (PMID 40243892, 2025).
breast carcinoma (5 papers, 2022 to 2025). "In other cancers, the transcription factor Yin Yang 1 increased FAM111B transcription activity and promoted the malignant development of breast cancer." (PMID 35406786, 2022). "High expression of FAM111B is correlated with poor outcome in breast cancer, and FAM111B was suggested to be important for cell proliferation, migration, and invasion in breast cancer." (PMID 36589246, 2022). "In recent years, there is increasing evidence suggesting FAM111B gene is relevant to tumorigenesis and development, including in pancreatic cancer, lung adenocarcinoma (LUAD), breast cancer, papillary thyroid cancer (PTC), ovarian cancer, hepatocellular carcinoma (HCC), and gastric cancer." (PMID 37958297, 2023).
hepatocellular carcinoma (5 papers, 2023 to 2025). A malignant tumor that arises from hepatocytes. "In hepatocellular carcinoma, FAM111B elevates TACC3 expression, thereby activating the PI3K/AKT signaling pathway." (PMID 40390043, 2025). "A Recent study of hepatoma cells showed that silencing FAM111B induced cell cycle arrest (G0/G1), and reduced cell migration and invasion abilities." (PMID 39337462, 2024).
lung carcinoma (4 papers, 2021 to 2024). "The only hypermethylated position in this comparison was associated with FAM111B, a nuclear serine protease that can promote proliferation, migration, and invasion in lung cancer, while its suppression induces cell apoptosis in cancer." (PMID 34941772, 2021). "Among these genes, the expression of two genes (CDCA3: p = 0.0002 and FAM111B: p = 0.0004) had a significant impact on the prognosis of lung cancer patients." (PMID 39337462, 2024). "The results demonstrated that there was no direct mutual exclusion or co-expression relationship between mutations of FAM111B and ZWINT and common mutations of lung cancer." (PMID 35406786, 2022). "Using cbioportal tool, the mutations of FAM111B and ZWINT in 3513 patient samples were compared with those closely related to lung cancer driver genes from 10 databases, including TCGA." (PMID 35406786, 2022). "Family with sequence similarity 111 member B (FAM111B) is a 16 kb gene situated on human chromosome 11q12.1, which has shown functions in various cancer types, including thyroid cancer, pancreatic adenocarcinoma, lung cancer, and cervical cancer." (PMID 36761753, 2023).
pancreatic cancer (4 papers, 2021 to 2025). "We linkour chromosomal instability data to the role of FAM111B incancer predisposition, pointed out by its implication in DNA-repair pathways andthe outcome of pancreatic cancer in 2 out of 17 adult POIKTMP patients." (PMID 34358284, 2021). "Upstream of FAM111B, a combination of metformin and aspirin has been demonstrated to markedly reduce FAM111B levels in pancreatic cancer cells, with “cholesterol biosynthesis,” “G1/S checkpoint regulation,” and “axon guidance” signaling pathways exhibiting significant enrichment." (PMID 40781291, 2025). "Immunohistochemical results showed that among the 8 CRGs: CEP55, FAM111B, MRPL3, MET, and KNSTRN had higher protein expression in pancreatic cancer tissues, while on the contrary, the protein expression of DHX30 in normal pancreas was significantly higher than that in pancreatic cancer tissues." (PMID 40677006, 2025).
thyroid cancer (4 papers, 2022 to 2025). "Additionally, research on lung adenocarcinoma and thyroid cancer has demonstrated that FAM111B is associated with immune-cell infiltration and positively correlates with immune checkpoints, including PDL-1 and CTLA-4." (PMID 40243892, 2025). "Moreover, studies have shown that FAM111B affects the T-cell balance in thyroid cancer and LUAD." (PMID 40243892, 2025). "In a real-world experiment, the RT-qPCR results were consistent with the bioinformatic analysis, confirming that ADAMTSL4, DOCK6, FAM111B, and SEMA6B were expressed at higher levels in thyroid cancer cells (p < 0.05), while MRPS10 and PSMB7 were expressed at lower levels (p < 0.05)." (PMID 36761753, 2023).
bladder cancer (2 papers, 2023 to 2024). "Our study identified FAM111B as an oncogene that promotes the tumorigenesis, progression, and metastasis of bladder cancer." (PMID 37958297, 2023). "In conclusion, we have demonstrated a strong correlation between the expression of FAM111B gene and the development, progression, and metastasis of bladder cancer (BLCA)." (PMID 37958297, 2023). "Thus, FAM111B gene is expected to serve as a promising molecular target for the therapy of bladder cancer." (PMID 37958297, 2023).
esophageal cancer (2 papers, 2024 to 2025). A primary or metastatic malignant neoplasm involving the esophagus. "Notably, FAM111B has been implicated in DNA replication and DNA damage-repair pathways in esophageal cancer." (PMID 40781291, 2025).
glioma (2 papers, 2023 to 2025). A benign or malignant brain and spinal cord tumor that arises from glial cells (astrocytes, oligodendrocytes, ependymal cells). "The multivariate analysis corroborated these findings, underscoring the role of high FAM111B expression as an independent risk factor for glioma prognosis." (PMID 40390043, 2025). "We established FAM111B as an independent prognostic marker for gliomas and a credible diagnostic indicator through both univariate and multivariate analyses." (PMID 40390043, 2025). "Additionally, we explored the association between FAM111B expression and clinical characteristics of gliomas." (PMID 40390043, 2025). "To assess the prognostic significance of FAM111B in glioma patients and its association with clinical characteristics, we conducted Kaplan–Meier survival analyses for overall survival (OS) and disease-free survival (DFS) using patient data from the TCGA database." (PMID 40390043, 2025). "This is the first study to demonstrate that FAM111B plays a crucial role in the proliferation, migration, and invasion of glioma cells." (PMID 40390043, 2025). "To investigate the mechanisms by which FAM111B influences glioma biology, we categorized the dataset into two groups based on FAM111B expression: those with expression above (upregulated) or below (downregulated) the median value." (PMID 40390043, 2025). "In summary, these findings underscore the significance of FAM111B as a pivotal element in predicting the prognosis and clinical outcomes of patients with gliomas." (PMID 40390043, 2025). "In conclusion, our study presents novel evidence highlighting FAM111B’s significant role in glioma cell oncogenic properties." (PMID 40390043, 2025). "To further elucidate the functional roles of FAM111B in gliomas, we employed lentiviral vectors for the overexpression and stable knockdown of FAM111B in glioma cell lines." (PMID 40390043, 2025). "FAM111B is capable of enhancing the proliferation, invasion, and migration capabilities of glioma cells and promotes the malignant progression of glioma via the PI3K/Akt signaling pathway." (PMID 40390043, 2025). "We verified the difference in FAM111B expression in glioma tissues and cell lines and constructed high- and low-expression FAM111B cell lines." (PMID 40390043, 2025). "We examined FAM111B expression in samples from patients with glioma and healthy controls using TCGA_GBM&LGG and CGGA databases, as well as the GSE4381, GSE76070, and GSE153692 datasets." (PMID 40390043, 2025). "We also found that FAM111B regulated glioma cell proliferation, migration, and invasion via the PI3K/AKT pathway." (PMID 40390043, 2025). "Consistent with our earlier observations, these glioma cell lines exhibited significant FAM111B overexpression compared to NHAs." (PMID 40390043, 2025). "Our findings revealed that FAM111B expression was elevated in glioma tissues compared to that in normal tissues." (PMID 40390043, 2025). "Using these FAM111B-associated DEGs, we further explored the potential regulatory roles of FAM111B in gliomas by conducting Gene Ontology (GO) and Kyoto Encyclopedia of Genes and Genomes (KEGG) analyses." (PMID 40390043, 2025). "Collectively, these results suggest that FAM111B overexpression promotes the malignant properties of glioma cells, whereas its knockdown inhibits these oncogenic processes." (PMID 40390043, 2025). "The objective of this study was to clarify how FAM111B contributes to the aggressive characteristics of gliomas and to uncover the specific molecular pathways involved." (PMID 40390043, 2025). "Analysis of the TCGA_GBM&LGG and CGGA databases revealed elevated FAM111B expression in glioma tissues." (PMID 40390043, 2025). "We found that FAM111B was significantly overexpressed in glioma tissues compared to the adjacent tissues by analyzing data from the TCGA_GBM&LGG and CGGA databases." (PMID 40390043, 2025).